CASC9 (cancer susceptibility 9)
Synonyms: LINC00981; ESCCAL-1; linc-JPH1; ESSCAL1
Gene: Long non-coding RNA gene on chromosome 8 (75,120,407 to 75,352,327, reverse strand). Ensembl gene ENSG00000249395.
Diseases named in the same sentence as CASC9 in open-access papers:
CASC9 is named in the same sentence as 43 diseases in open-access papers, as found by Europe PMC text mining. Sharing a sentence is not in itself a finding about the gene and the disease. The quoted sentences say what the papers report.
esophageal squamous cell carcinoma (24 papers, 2014 to 2025). Esophageal squamous cell carcinoma (ESCC) is a type of esophageal carcinoma (EC) that can affect any part of the esophagus, but is usually located in the upper or middle third. "CASC9 was first described as an esophageal squamous cell carcinoma (ESCC)-associated lncRNA with increased expression in ESCC comparable to HOTAIR." (PMID 31412811, 2019). "CASC9 (Cancer susceptibility candidate 9) located on chromosome 8q21.11 was first described as an esophageal squamous cell carcinoma (ESCC)-associated lncRNA with increased expression in ESCC, comparable to HOTAIR in ESCC." (PMID 31412811, 2019). "Cancer susceptibility candidate 9 (CASC9), mapped to human chromosome 8q21.11, was originally identified as an esophageal squamous cell carcinoma‐associated lncRNA." (PMID 27431358, 2016). "Emerging studies have found that long noncoding RNA cancer susceptibility candidate 9 (CASC9) is highly expressed in various cancers, such as esophageal squamous cell carcinoma, nasopharyngeal carcinoma and hepatocellular carcinoma, implying a crucial carcinogenic effect of this lncRNA13–19." (PMID 30674868, 2019). "Upregulated expression of LAMC2, an indicator of progression in esophageal squamous cell carcinoma (ESCC), is caused by lncRNA Cancer Susceptibility 9 (CASC9) interacting with CREb-binding proteins and is common in patients." (PMID 37889117, 2023). "In another study, lncRNA CASC9 (cancer susceptibility 9) was revealed to be associated with the prognosis and metastasis of esophageal squamous cell carcinoma (ESCC)." (PMID 33520725, 2020). "Studies on esophageal squamous cell carcinoma and hepatocellular carcinoma have shown that high expression of CASC9 activates the PI3K/AKT signaling pathway, promoting the proliferation, invasion and metastasis of cancer cells." (PMID 30674868, 2019). "Emerging evidence suggests that CASC9 regulates the AKT signaling pathway in esophageal squamous cell carcinoma and hepatocellular carcinoma." (PMID 30674868, 2019). "In esophageal squamous cell carcinoma, CASC9 downregulates programmed cell death 4 protein." (PMID 35427373, 2022). "However, recent studies have determined that CASC9 is highly expressed in many cancers, such as esophageal squamous cell carcinoma, nasopharyngeal carcinoma and hepatocellular carcinoma." (PMID 30674868, 2019). "Moreover, the lncRNA CASC9 was found to be markedly upregulated in esophageal squamous cell carcinoma tissues, and knockdown of CASC9 significantly suppressed esophageal squamous cell carcinoma cell migration and invasion." (PMID 28220683, 2017). "A study reported that the lncRNA CASC9 was significantly upregulated in esophageal squamous cell carcinoma (ESCC) species." (PMID 39408810, 2024). "For instance, CASC9 promoted esophageal squamous cell carcinoma (ESCC) progression by negatively regulating PDCD4 expression through recruiting EZH2." (PMID 36494339, 2022). "The CASC9 oncogene is highly expressed in esophageal squamous cell carcinoma (ESCC), ovarian cancer, BC, lung cancer, papillary thyroid cancer, and bladder cancer." (PMID 34711117, 2021). "Upregulation of the lncRNA CASC9 in esophageal squamous cell carcinoma (ESCC) was correlated with metastasis and poor prognosis." (PMID 29891810, 2018). "The objective of the study was to investigate the expression and functions of CASC9 in esophageal squamous cell carcinoma (ESCC)." (PMID 27431358, 2016). "CASC9 also recruiting EZH2 to PDCD4 promoter and alters H3K27me3 level and subsequently promotes esophageal squamous cell carcinoma metastasis by activating PDCD4 expression." (PMID 32677984, 2020). "CASC9 activates LAMC2 expression through altering LAMC2 promoter H3K27me3 level by recruits CBP and subsequently promotes esophageal squamous cell carcinoma metastasis." (PMID 32677984, 2020). "CASC9 was reported to promote malignancy in ovarian cancer, colorectal cancer (CRC), lung cancer, esophageal squamous cell carcinoma (ESCC), and BC." (PMID 34711117, 2021).
esophageal squamous cell carcinoma (continued). "In addition, a positive correlation between LAMC2 and lncRNA CASC9 was demonstrated, which was consistent with the study published in 2018, showing that lncRNA CASC9 and LAMC2 have positive correlation in esophageal squamous cell carcinoma by interacting with CREB-binding protein." (PMID 34612783, 2021). "LncRNA CASC9 was defined as an oncogene in various cancers, such as breast cancer, colorectal cancer (CRC), non-small cell lung cancer (NSCLC), and esophageal squamous cell carcinoma but never in OS." (PMID 36266695, 2022).
gastric cancer (16 papers, 2014 to 2024). A primary or metastatic malignant neoplasm involving the stomach. "CASC9 was firstly reported in esophageal cancer as an oncogene and was subsequently confirmed to be associated with the occurrence and development of several cancers, such as breast cancer, gastric cancer and colorectal cancer." (PMID 36266695, 2022). "LncRNA cancer susceptibility candidate 9 (CASC9), whose expression is associated with poor differentiation, invasion and lymph node metastases of gastric cancer, has been reported to promote resistance to ADR of gastric cancer cells through up-regulating expression of MDR1 protein." (PMID 32192494, 2020). "It has been discovered that the lncRNA cancer susceptibility candidate 9 (CASC9), whose expression is linked to poor differentiation, invasion, and lymph node metastases in GC, increases the expression of the MDR1 protein to make gastric cancer cells resistant to ADR." (PMID 38294554, 2024). "CASC9 expresses highly by miR-125b/neuregulin-1 in hemangioma, colon, lung, and gastric cancers, etc.." (PMID 35427373, 2022). "Recently, several studies have found that lncRNA CASC9 is overexpressed in cancers, and it plays oncogenic roles in human cancer types, including colorectal and gastric cancers." (PMID 34612783, 2021). "A pan-cancer analysis revealed that CASC9 is also strongly overexpressed in different other entities including bladder, liver, lung and stomach cancers and especially in squamous cell carcinoma (SCC) of the lung." (PMID 31412811, 2019). "Analysis of TCGA pan-cancer data revealed significant overexpression of CASC9 across different other entities including bladder, liver, lung and stomach cancers and especially in squamous cell carcinoma (SCC) of the lung." (PMID 31412811, 2019). "Similar results were reported for gastric cancer, where CASC9 was also highly expressed in chemoresistant cell lines, and for hepatocellular carcinoma." (PMID 31412811, 2019). "In this study, we have found that CASC9 was overexpressed in gastric cancer (GC) compared to normal gastric tissue." (PMID 28146436, 2017). "The expression of CASC9 in gastric cancer cell lines, BGC823 and SGC7901 cells (4.21 ± 0.25, 3.24 ± 0.20), were higher than that in control normal gastric epithelial cells (GES-1) (P < 0.05)." (PMID 28146436, 2017). "Besides, high CASC9 expression exerted a tumor suppressor role in gastric cancer (GC) and positively correlated with lymph node metastasis and TNM stage, which was also similar in STAD in our study." (PMID 36445051, 2023). "Other lncRNA including ELFN1-AS1, CASC9, SLCO4A1-AS1, DSCR8 and so on are all found to be studied previously and associated with at least one cancer type, which demonstrates that these lncRNAs can indeed capture the oncogenic features of gastric cancer." (PMID 34728653, 2021). "In addition, lncRNAs PVT1, HOTAIR and CASC9 also promoted PTX resistance of gastric cancer through modulating expression of various genes." (PMID 32192494, 2020). "Simultaneously, several research groups revealed that CASC9 was also upregulated in many cancer types, including esophageal cancer, gastric cancer (GC), pancreatic ductal adenocarcinoma (PDAC), and nasopharyngeal carcinoma (NC)." (PMID 29511340, 2018). "Multiple onco-lncRNAs, such as HOTAIR, CASC9, MRUL, UCA1, D63785, NEAT1 and HULC, are involved in ADR resistance in gastric cancer." (PMID 32192494, 2020). "In two gastric cancer cell lines, BGC823 and SGC7901, CASC9 were both overexpressed compared to that of normal gastric epithelial cell (GES-1)." (PMID 28146436, 2017). "Besides, we firstly demonstrated that silencing CASC9 enhances the sensitivity of NPC cells to cisplatin and paclitaxel, which is also consistent with the research in gastric carcinoma." (PMID 35419295, 2022).
breast carcinoma (13 papers, 2014 to 2024). "Similarly, lutein in combination with long non-coding RNA cancer susceptibility (CASC9) was evaluated for the antiproliferative activity in MCF-7 breast cancer cells." (PMID 35565917, 2022). "Prior studies have revealed a strong correlation of CASC9 with hepatocellular carcinoma, breast cancer, osteosarcoma, and pancreatic cancer progression and its role in enhancing tumor resistance to gefitinib and gemcitabine." (PMID 39115621, 2024). "Results showed that lutein down regulated the expression of CASC9 and up regulated the expression of miR-590-3p that eventually resulted in inhibition of breast cancer proliferation." (PMID 35565917, 2022). "lncRNA CASC9 is overexpressed in many human cancers, including gastric, esophageal squamous cell, and breast cancers." (PMID 34612783, 2021). "LncRNA CASC9 is a widely studied lncRNA in cancer, and it is a common oncogene that can promote the growth and proliferation of cancer cells in esophageal cancer, oral cancer, rectal cancer, breast cancer, and so on." (PMID 33585468, 2020). "In addition, we investigated whether CASC9 promotes the malignancy of breast cancer cells by interacting with miR-590-3p." (PMID 34711117, 2021). "Further reported CASC9 target genes were CDK4, CyclinD1 (CCND1), E-Cadherin (CDH1) and BCL2 in lung adenocarcinoma, ESCC cells, oral squamous cell carcinoma and in breast cancer." (PMID 31412811, 2019).
bladder cancer (11 papers, 2014 to 2024). "CASC9 was highly expressed in bladder cancer cells and tissues, and the prognosis of bladder cancer patients with high expression of CASC9 was poor." (PMID 35578597, 2022). "In fact, there are many reports that CASC9 is involved in non-small cell lung carcinoma, bladder cancer, thyroid cancer, hepatocellular carcinoma, nasopharyngeal cancer, and lung cancer." (PMID 34017854, 2021). "This study found that CASC9 expression was markedly upregulated in bladder cancer and related to histological grade, TNM stage and prognosis." (PMID 32677984, 2020). "The CASC9/miR-497-5p/ FZD6 axis provides insights for regulatory mechanism of bladder cancer, and new strategies for clinical practice." (PMID 32677984, 2020). "Loss-of-function experiments were performed to identify the functions of CASC9 in tumor growth and metastasis of bladder cancer in vitro and in vivo." (PMID 32677984, 2020). "Analysis of a further tissue set comprising bladder cancers with different histologies by RT-qPCR demonstrated CASC9 overexpression predominantly in urothelial carcinomas with squamous differentiation or pure squamous bladder cancers." (PMID 31412811, 2019). "CASC9 was also significantly overexpressed in many bladder cancer specimen, particularly in urothelial cancers with squamous differentiation (MIX) and especially strongly in pure squamous carcinoma of the bladder (SCC)." (PMID 31412811, 2019). "For instance, CASC9 could sponge miR−758−3p to promote cell proliferation and epithelial−mesenchymal transition in bladder cancer by regulating TGF−β signaling pathway." (PMID 35419295, 2022). "The results of colony formation assays, CCK-8 assays, EdU assays, transwell assays, mouse xenograft models, and tail vein injection lung metastasis model showed that CASC9 could promote bladder cancer cells growth and metastasis both in vitro and in vivo." (PMID 35578597, 2022). "The expression level of CASC9 was determined in a total of 106 patients with bladder cancer." (PMID 32677984, 2020). "In summary, lncRNA CASC9 plays a critical regulatory role in bladder cancer." (PMID 32677984, 2020). "Furthermore, further experiments demonstrated that knockdown of CASC9 inhibited growth and metastasis of bladder cancer cells (BCCs) in vitro and in vivo." (PMID 32677984, 2020). "Knockdown of CASC9 inhibited tumor growth and metastasis of bladder cancer in vitro and in vivo." (PMID 32677984, 2020). "However, the clinical significance and molecular mechanism of CASC9 in bladder cancer is still unknown." (PMID 32677984, 2020). "Mechanistically, through FISH experiments, luciferase reporter experiments, and RIP experiments, we proved that CASC9 regulated the expression of TK1 by adsorbing miR-195-5p, thereby exerting an oncogenic effect in bladder cancer." (PMID 35578597, 2022). "Meanwhile, we found knockdown of CASC9 decreased FZD6 and inhibited EMT of bladder cancer cells in vivo." (PMID 32677984, 2020). "Taken together, our findings support that the CASC9/miR-195-5p/TK1 axis is a critical pathway in the tumorigenesis and progression of bladder cancer, implicating a new therapeutic direction for the treatment of bladder cancer." (PMID 35578597, 2022). "Mechanistically, we found that CASC9 functions as a miRNA sponge to positively regulate FZD6 expression and subsequently activates Wnt/β-catenin signaling pathway, thus playing an oncogenic role in bladder cancer pathogenesis." (PMID 32677984, 2020). "The results indicated that CASC9 does not affect the apoptosis of bladder cancer cells." (PMID 32677984, 2020). "Moreover, CASC9 and FZD6 were co-expressed in bladder cancer cells." (PMID 32677984, 2020).
colorectal cancer (11 papers, 2019 to 2023). A primary or metastatic malignant neoplasm that affects the colon or rectum. "Evidence indicates that other members of the CASC family (CASC2, CASC11, CASC9) could be associated with enhanced or reduced proliferation, invasion, and apoptosis in cervical and colorectal cancers." (PMID 35887085, 2022). "CPSF3 (Polyadenylation specificity factor 3) protein interacts with a lncRNA CASC9 (Cancer Susceptibility 9), and knockdown of CPSF3 mimicked the effects of CASC9 knockdown in colorectal cancer cells." (PMID 37042179, 2023). "TGFβ2 and p-SMAD3 levels were reduced in CASC9-knockdown cells, whereas their levels were increased in CASC9 overexpressing colorectal cancer cells." (PMID 33511320, 2021). "lncRNA CASC9 expression was increased in primary colorectal cancer samples, and CASC9 initiates CRC development by regulating miR‐193a‐5p/ERBB2 axis." (PMID 32533587, 2020). "While in colorectal cancer, CASC9 interacted with CPSF3 to regulate TGF-β signal transduction." (PMID 36248984, 2022). "CASC9 has been reported to be overexpressed in papillary thyroid cancer and colorectal cancer." (PMID 35578597, 2022). "CASC9 was found to be frequently overexpressed in colorectal cancers." (PMID 33511320, 2021).
esophageal cancer (10 papers, 2015 to 2023). A primary or metastatic malignant neoplasm involving the esophagus. "Cancer Susceptibility Candidate 9 (CASC9) is a novel gene generating long non-coding RNA (lncRNA) with oncogenic potential that was first identified in esophageal cancer." (PMID 28146436, 2017). "The level of CASC9 expression was determined in 44 paired esophageal cancer samples and adjacent, histologically normal tissues by qRT‐PCR, and normalized to 18S." (PMID 27431358, 2016). "Similarly, CASC9, which is up-regulated in esophageal cancer tissue, suppressed cell migration and invasion in vitro in knockdown experiments in that cancer type." (PMID 30416681, 2018). "Moreover, a recent study showed that CASC9 expression is upregulated and regulates cell migration and invasion in esophageal cancer." (PMID 28220683, 2017). "lncRNA CASC9 was significantly up-regulated in esophageal cancer tissues." (PMID 28388588, 2017). "Furthermore, CASC9 knockdown significantly inhibited esophageal cancer cell migration and invasion in vitro." (PMID 27431358, 2016). "The results indicated that CASC9 is significantly upregulated in ESCC tissues and may represent a new marker of poor prognosis and a potential therapeutic target for esophageal cancer intervention." (PMID 27431358, 2016).